IL6 (interleukin 6)
Diseases named in the same sentence as IL6 in open-access papers (continued):
Sharing a sentence is not in itself a finding about the gene and the disease.
COVID-19 (continued). "Systemic values of IL-1β (p = 0.001), IL-6 (p = 0.001), IL-10 (p = 0.026), IL-23 (p = 0.001), IL-33 (p = 0.001), and Gal-1 (p = 0.001) were significantly higher in COVID-19 patients in stage III compared to patients in stage I and II." (PMID 35075140, 2022). "While corticosteroids have a substantial effect among critically ill patients with COVID-19, the effect of specific therapies, for example, tocilizumab as a monoclonal humanized antibody against IL-6, appears to be significantly smaller." (PMID 34608263, 2022). "In patients with cancer, autoimmune diseases, severe respiratory infections [e.g. coronavirus disease 2019 (COVID-19)] and wound healing, IL-6 plays a critical role in modulating the systemic and local microenvironment." (PMID 35867145, 2022). "Increased production of interleukins (IL-6, IL-10) and coagulopathy lead to high fatality rates in hospitalized COVID-19 patients." (PMID 36397967, 2022). "Interleukin-1 and IL-6 are proinflammatory cytokines which have been demonstrated to be major contributors to development of hyperinflammatory response in COVID-19." (PMID 36422492, 2022). "While pGSN and anti-spike IgG titers together strongly predict COVID-19 severity and death, the combination of pGSN and IL-6 was a significant predictor of milder disease and favorable outcomes." (PMID 36148234, 2022). "Specifically, ncfDNA was correlated with cytokines/chemokines such as IL-15, IL-8, Eotaxin-3, IL-1β, IL-10, IL-16, VEGF, IL-6, IL-7, GM-CSF and IL-1α in SOTRs with COVID-19." (PMID 35075453, 2022). "Tocilizumab, a IL-6R monoclonal antibody that prevents IL-6 binding and reduces IL-6 signaling, was mostly used in patients with the advanced stage of COVID-19 to prevent the cytokine storm." (PMID 35741101, 2022). "The expression level of RIG-I and IL-6 were clearly higher in patients with symptomatic COVID-19 compared to healthy controls, and also, they were upregulated in nonsymptomatic patients in comparison to the control group." (PMID 36081604, 2022). "During COVID-19, many cytokines such as IL-6, IL-10, and TNF-α are markedly higher, whereas T lymphocytes are much lower." (PMID 36278672, 2022). "The downregulation of these miRNAs in patients with COVID-19 leads to IL-6/IL-6R hyperactivation by directly targeting the 3'UTR of IL-6/IL-6R, thereby enhancing the cytokine storm induced by SARS-CoV-2 infection." (PMID 35928726, 2022). "Inflammation is primarily dependent upon IL-6 from elevated plasma samples of the patients which correlates the co-infection of COVID-19 with that of gynaecological cancer and other malignancies." (PMID 36299504, 2022). "In order to elucidate if IL-6 signalling was helpful to discriminate severe COVID-19, we analysed serum levels of IL-6, sIL-6R, and sgp130." (PMID 35634332, 2022). "A higher number of CD4+ cells expressing GM-CSF and IL-6 was reported in COVID-19 patients admitted to intensive care units." (PMID 36034704, 2022). "In COVID-19, purUUpurU drives upregulation of IL-6 expression which results in a marked acute phase reaction." (PMID 36420234, 2022). "Plasma levels of amino acids 3-methylhistidine and 4-hydroxyproline, originating from actin/myosin and collagen metabolism, respectively, were also largely reduced in COVID-19 patients with high IL-6 levels." (PMID 35064792, 2022). "It seems to be an article of faith today among investigators and physicians that treating patients with COVID-19 or cancer patients with anti-IL-6 mAb, which “neutralize” IL-6 bioactivity in cell culture, should have similar neutralizing effects in vivo." (PMID 35406728, 2022). "The IL-6 can also be used as an early warning diagnosis and treatment index of COVID-19 and also treated as the molecule for assessing the severity of infection and judge prognosis and the response to treatment." (PMID 36016137, 2022).
COVID-19 (continued). "The prognostic value of several biomarkers (e.g. CRP, IL-6, ferritin) and clinical scores for predicting disease progression in COVID-19 at early disease stages, e.g. at hospital admission, is now well established." (PMID 36812516, 2022). "Treatment with the IL-6-specific monoclonal antibody tocilizumab normalized sodium levels in patients with COVID-19, in conjunction with overall disease improvement." (PMID 36714113, 2022). "In all seven studies, the COVID-19 patients had relatively mild symptoms, and the IL-6 level tended to be within the normal range." (PMID 35222429, 2022). "COVID-19 triggers signaling cascades in response to viral contact, leading to the release of type I interferons, cytokines, and chemokines (IL-1β, IL-2, IL-6, IL-17, TNF-α, G-CSF, IFN-γ, CXCL10, CCL2 and CCL3, i.e., the cytokine storm)." (PMID 35982898, 2022). "Proteomic analysis highlighted a cytokine storm in the serum of patients with COVID-19, with elevated expression levels of IL-6, CXCL10, CXCL11, IFNγ, MCP-2, and MCP-3 detected in infected patients relative to healthy controls." (PMID 35303909, 2022). "Although further studies are necessary to establish treatments for COVID-19 by suppressing IL-6, macrophage stimulation by N protein should be avoided to prevent the development of cytokine storm." (PMID 35577892, 2022). "In the last study, the levels of xanthines correlated with pro-inflammatory cytokines, such as IL-6, in severe patients corroborating the link between the disturbances in metabolic pathways and hyper-inflammation in COVID-19." (PMID 35102215, 2022). "For the hyperinflammation assessment, the markers C-reactive protein(CRP) and/or ferritin and/or IL-6 were employed in their investigation, as both ferritin and IL-6 have been previously shown increases in severe COVID-19 cases in contrast to survivors." (PMID 35663932, 2022). "Clinical characteristics among non-diabetic (NDM) and prediabetic (PDM) patients with Coronavirus Disease 2019 (COVID-19) stratified according to low or high IL-6 production." (PMID 35898449, 2022). "Regarding COVID-19, in a meta-analysis review, it has been demonstrated that serum levels of IL-6 are significantly increased in severe forms of COVID-19." (PMID 36289890, 2022). "SDE miRNAs in COVID-19 patients were significantly correlated with proinflammatory cytokines such as IL-6, IL-12, IP10, and TNFα, while healthy and infected patients showed different correlation patterns (respectively)." (PMID 35130828, 2022). "COVID-19 patients have high levels of pro-inflammatory cytokines and chemokines such as IL-1β, IL-2, IL-6, IL-7, IL-10, IFN-γ, TNF-α, G-CSF, CCL2, and CXCL10." (PMID 35782361, 2022). "Discriminative accuracy for hospitalisation was highest for IL-6 and CRP in all three diagnoses (in COVID-19, area under the curve (AUC) for IL-6 0.899 [95%CI 0.850–0.948]; AUC for CRP 0.922 [95%CI 0.879–0.964])." (PMID 35622838, 2022). "In the most severe cases of COVID-19, IL-6 levels are greatly elevated, and this is one of the factors that leads to cytokine production." (PMID 35958594, 2022). "PG is associated with an increase in proinflammatory cytokines, including interleukin-12 (IL-12), IL-23, tumor necrosis factor (TNF)-alpha, and IL-6 9, which are also involved in the pathogenesis of COVID-19." (PMID 35600185, 2022). "Of note, the severity of pulmonary complications in COVID-19 seems to be closely related to IL-6 and TNF-α peak levels." (PMID 35211011, 2022). "From clinical evidence, IL-6 is the more frequently reported cytokine elevated in COVID-19, which mediates acute inflammatory responses in the disease." (PMID 35742845, 2022). "To detect an accumulation of cytokines both in the maternal serum of pregnant women with COVID-19 and in fetuses, we decided to perform an ELISA test for IL-6 and IL-8 on serum and cord blood." (PMID 35408809, 2022).
COVID-19 (continued). "COVID-19 upregulates the expression of proinflammatory cytokines such as interleukin-6 and tumor necrosis factor-alpha, triggering a cytokine storm that recruits macrophages and causes inflammatory reactions." (PMID 35843961, 2022). "In the present cohort of COVID-19 patients, thrombomodulin, IL-6, FVIII, VWF:Ag, sEPCR, sC5b9, tPA, PAI-1 activity, C4, ICAM-1 and VCAM-1 plasma levels were higher than normal ranges, in line with previous studies that included patients with a severe disease." (PMID 36143072, 2022). "It is worth noticing that IL-6 levels were also higher in the controls compared to the COVID-19 patients; however, the latter were receiving dexamethasone as per international guidelines." (PMID 35207659, 2022). "Anti-inflammatory cytokine IL-10 was shown to be more strongly related with disease progression and severe acute kidney injury than the proinflammatory cytokines IL-6 and IL-8 in COVID-19 patients with severe sickness." (PMID 35958594, 2022). "NOTCH signaling can also upregulate IL-6 and pro-inflammatory mediators induced to hyperactivation in COVID-19." (PMID 35992174, 2022). "The role of cytokines in the physiopathology of COVID-19 has been widely documented, and the circulant levels of cytokines such as Il-6 and TNF-alpha are strong predictors of COVID-19 progression." (PMID 36012503, 2022). "Bacterial and endotoxin translocation in COVID-19 induces a significant increase in several markers of systemic inflammation, such as IL-6, IL-1b, IL-8, MCP-1, IP-10 and TNF-a." (PMID 35630492, 2022). "The concentration of IL-6 was found to be significantly correlated with the severity of COVID-19 with a directly proportional relationship (p < 0.001)." (PMID 33983525, 2022). "The concentration of IL-6 was found to be significantly correlated with the severity of COVID-19 with a directly proportional relationship." (PMID 33983525, 2022). "There is evidence that shows elevated levels of inflammatory and anti-inflammatory cytokines, including interferon (IFN)-γ, interleukin (IL)-6, IL-β, IL-8, and IL-10 in the COVID-19 patients with severe symptoms." (PMID 36038915, 2022). "Immune dysregulation with systemic inflammation (especially interleukin-6 along with complement activation) and thrombosis has been proposed for the pathogenesis of severe COVID-19." (PMID 36397967, 2022). "It has been reported that KL-6 levels significantly correlated with other inflammatory biomarkers, such as CRP, neutrophils, and IL-6 levels in COVID-19." (PMID 36295478, 2022). "Preliminary studies have shown that leronlimab treatment of COVID-19 patients induced a reduction of plasma IL-6, restoration of the CD4/CD8 ratio, and resolution of SARS-CoV-2 plasma viremia." (PMID 35572540, 2022). "The most important inflammatory mediators released by immune cells during the “cytokine storm” are IFN-α, IFN-γ, IL-1β, IL-6, IL-12, IL-18, IL-33, TNF-a, and TGF-β and they are associated with different clinical features of COVID-19." (PMID 36298472, 2022). "IL-6, the key cytokine in cytokine storm/MIS associated with severe COVID-19, has the opposite effect." (PMID 36430430, 2022). "Specifically, elevated IL-6 and IL-10 levels observed in COVID-19, can inhibit NK cytotoxicity, mediated by Granzyme-B production, Fas/FasL (Fas ligand) interaction and CD16 binding with the Fc (constant fraction) of antibodies." (PMID 35336077, 2022). "Our study focussed on the predictive utility of C-reactive protein, Interleukin-6, D-dimer and Procalcitonin in assisting the management of COVID-19 patients with adverse clinical effects." (PMID 35261542, 2022). "A significant cytokine storm has been described in patients with severe COVID-19, with elevated serum levels of pro-inflammatory cytokines such as interleukin (IL) 1, IL-6, IL-10, and tumor necrosis factor (TNF)-α." (PMID 35453522, 2022).
COVID-19 (continued). "It should be noted that severity score (SOFA & APACHE II) and cytokine levels (IL-6, C-reactive protein) can be used to discuss the indication for therapeutic plasma exchange therapy and to monitor response in COVID-19 patients." (PMID 36360368, 2022). "In our study, inflammatory cytokines TNF-a, C-Reactive Protein (CRP), and Interleukin 6 (IL-6) significantly differed between patients with moderate and severe COVID-19, indicating their potential as parameters for severity." (PMID 36556051, 2022). "IL-6, the core factor of “cytokine storm”, plays a pivotal role in the severity and high mortality of COVID-19." (PMID 35237162, 2022). "We analyzed the bacterial and fungal taxonomic profiles and loads of 232 gut and respiratory samples and we measured the blood levels of Interleukin 6, IgG, and IgM in COVID-19 patients." (PMID 36555453, 2022). "Based on the COVID-19 cytokine literature, we identified 6 cytokines (IL-1β, IL-2, IL-6, IL-8, IL-10, and TNF-α) commonly found in critically ill COVID-19 patients." (PMID 35033181, 2022). "The serum IP-10, MCP-1, MIP-1α, and IL-6 levels among critically ill COVID-19 patients were significantly higher than that in patients with moderate disease and healthy controls (p < 0.001)." (PMID 35822078, 2022). "Even modest COVID-19 can induce proinflammatory effects, seen by elevated IL-1b, IL-6, TNFα, MCP-1 & IP-10, leading to insulin resistance." (PMID 35165505, 2022). "IL-6 is an indicator of the severity of COVID-19, referencing the Diagnosis and Treatment Protocol for Novel Coronavirus Pneumonia (Trial Version 7)." (PMID 36233840, 2022). "When this trial was designed, there were no pharmacological treatments for COVID-19, although recent trials have demonstrated dexamethasone and IL-6 antagonism reduced 28-day mortality in mechanically ventilated patients with COVID-19." (PMID 35562778, 2022). "All examined inflammatory biomarkers (CRP, fibrinogen, serum ferritin and IL-6) were higher in patients with severe COVID-19 (p < 0.001) as well." (PMID 35330457, 2022). "In comparison, IL-6 plasma levels within 24 h of ICU admission presented an AUC of 0.62 in a cohort of critically ill COVID-19 patients, whereas sRAGE in our cohort presented a higher AUC of 0.82, suggesting a better prognosis performance." (PMID 35956186, 2022). "For the MGH cohort, comparable tertile groups were created according to TNF-α, IL-1β, IL-6 and IL-8 at admission for both mild and severe COVID-19." (PMID 35938070, 2022). "A recent paper reported that elevated plasma levels of IL-6, IL-10 and IP-10 anticipated clinical progression of COVID-19 patients." (PMID 35563282, 2022). "The pharmacotherapy based on interleukin-6 inhibitor (tocilizumab) in COVID-19/SCD scenarios helps control cytokine storms and immune response dysregulation based on critical hypercytokinemia, neutrophilia, and lymphocytopenia." (PMID 35494937, 2022). "The diffusion of mAbs into the liver is likely higher than in local sites of IL-6 production, such as alveoli in patients with COVID-19." (PMID 35928820, 2022). "The key targets of Paxlovid against LUAD/COVID-19 were obtained through network pharmacology, the most important targets include IL6, IL12B, LBP." (PMID 36157452, 2022). "Large, randomized control trials are necessary to determine the effectiveness of IL-6 inhibition among COVID-19 patients." (PMID 36263178, 2022). "COVID-19 outcomes were also positively or equivocally affected by anti-IL-6 (tocilizumab) medication." (PMID 35054471, 2022). "The anti-cytokine and anti-viral activities of baricitinib are primarily responsible for the clinical and radiological recovery, a rapid reduction in the viral load, inflammatory markers, and IL-6 levels in COVID-19." (PMID 36330085, 2022). "The unrestrained secretion of TNF-ɑ, IL-1, IL-6, and IFN-γ are some of the pro-inflammatory cytokines underlying the pathogenesis of the severe and life-threatening disease conditions in COVID-19." (PMID 36094915, 2022).
COVID-19 (continued). "IL-6, one of the first plasma cytokines recognized as elevated during COVID-19,54 also exhibited a positive correlation with disease severity in our cohort." (PMID 35839768, 2022). "Among these cytokines was IL-6, confirming previous observations of its role in severe COVID-19 pathogenesis." (PMID 35386707, 2022). "C-reactive protein, interleukin-6, lactate dehydrogenase, and D-dimer levels are lower after therapeutic plasma exchange in critically ill adults with COVID-19." (PMID 36360368, 2022). "Our findings revealed low IL-6 levels in both the JSHT and control groups before and after the study, indicating that the included patients with COVID-19 had relatively low disease severity and low mortality risk." (PMID 35369061, 2022). "All tested biomarkers showed a modest role to predict post-acute long COVID-19, with comparative performance being recorded for ferritin, fibrinogen, and IL-6." (PMID 35741183, 2022). "Among all cytokines, interleukin-6 (IL-6) has an important position in COVID-19, not only because of its stimulating effects in cytokine storm, but also because of its cardiovascular effects." (PMID 35722133, 2022). "COVID-19 patients with elevated IL-6 levels and evidence of hyperinflammation had increased rates of more severe symptoms." (PMID 36503381, 2022). "According to the asymptomatic status of COVID-19 in the patient, values of interleukin (IL)-6, IL-8, ferritin, and C-reactive protein were in the normal range." (PMID 35779200, 2022). "The cytokine storm, the state of pro-inflammatory cytokines overproduction, corresponded to the COVID-19 adverse outcomes, as was seen when IL-6 was correlated to mortality and the need for ventilators in patients with COVID-19." (PMID 36457603, 2022). "To date, treatments with the objective to improve the quantity and quality of CD4+ T cells in COVID-19 have focused on addressing hyperactivation, anergy, or modulating specific cytokines, such as IL-1 and IL6." (PMID 36678366, 2022). "There is evidence that many pro-inflammatory cytokines and chemoattractant are elevated in COVID-19 patients, including IL-1β, IL-6, IL17, TNF-α, GM-CSF, and IFN-γ." (PMID 36034704, 2022). "We found up to seven cytokine/chemokines significantly increased in hospitalized COVID-19 patients; with IL-1RA, IP-10 and IL-6 being about two-fold or higher upregulated as compared to the normal values measured in the healthy individuals." (PMID 36557244, 2022). "Among these, changes in IL-6, IL-1β and TNF-α levels were the best documented in the hyperinflammatory response associated to COVID-19 and ARDS." (PMID 36466830, 2022). "First we assessed IL6 in SVC because of the association between interleukin (IL)-6 and low-grade inflammation in obese individuals, and the critical role of IL-6 in COVID-19 immunopathogenesis." (PMID 36137009, 2022). "It has been shown a gradual decrease in the IL-6 levels with higher levels in the age subgroup 20-50 years and 51-80 years of COVID-19 patient compared with the same age subgroups in the healthy controls." (PMID 36381078, 2022). "Increased amounts of cytokines (i.e. IL-6) are associated with lymphopenia with decreasing CD4+ and CD8+ cell counts, and severe lung injury in patients with COVID-19 that lead to death." (PMID 35533178, 2022). "The study showed that the IL-6 level was on the rise during the course of COVID-19, whereas that of insulin was on the decrease." (PMID 35530861, 2022). "Among the different antiviral cytokines, elevated levels of IL-10 and IL-6 are predictors of COVID-19 severity." (PMID 36440226, 2022). "This is similar to findings of positive regulation of genes encoding the activation of innate immune system, viral and IFN response, increase of proinflammatory macrophages and elevated IL-6 and IL-10 in severe COVID-19 cases." (PMID 35663963, 2022).